IL18 (interleukin 18)
Diseases named in the same sentence as IL18 in open-access papers (continued):
Sharing a sentence is not in itself a finding about the gene and the disease.
autoimmune disease (continued). "While little is known about the exact function of IL-18, it has been reported that the molecule is highly expressed in autoimmune diseases and may accelerate the production of anti-sperm antibodies that are a typical consequence of male subfertility caused by a systemic inflammation." (PMID 36555696, 2022). "However, it remains unknown how the IL-18/IL-18Rα signaling pathway functions in the immune response to autoimmune diseases such as rheumatoid arthritis." (PMID 31861496, 2019). "However, in a disease setting, such as autoimmune diseases, inborn disorders, or chronic inflammatory conditions, IL-18 can become dysregulated, leading to excessive inflammation which may result in a cytokine storm, tissue damage, organ failure, and even death." (PMID 39769266, 2024). "Pyroptosis is a form of lytic programmed cell death, and it aggravates autoimmune diseases progression via activating NOD-like receptors, especially the NLRP3 inflammasome and its downstream inflammatory factors IL (interleukin)-1β and IL-18." (PMID 37063905, 2023). "Here, we found that mROS are required for IL-12 plus IL-18-driven production of IFN-γ, an essential cytokine for inflammatory and autoimmune disease development." (PMID 35668079, 2022). "Comparison of rules for each disease revealed that TLR3, TLR5, IL18, IL18R1, and IL1R1 genes occurred in rules for all studied diseases, showing good discriminant power among studied autoimmune diseases as visualized by the Andrews curves." (PMID 31396542, 2019). "Notably, both HLA-I-specific and HLA-II-specific pGenes included known drug targets for autoimmune diseases, infectious diseases, and cancer such as LAG3, PDCD1, TNF, and ACE2 affected by HLA-I; and IL18, TREM2, VSIG4, and TLR1 by HLA-II." (PMID 39085222, 2024). "While IL-12 and IL-18 have demonstrated potential in promoting CAR T cell proliferation and persistence without preconditioning in murine models, their pro-inflammatory nature poses a significant challenge for their application in autoimmune diseases." (PMID 39697333, 2024). "In the event of infection, patients with autoimmune diseases have dysregulated innate and acquired immune responses that lead to overproduction and overresponse, mediated by pro-inflammatory cytokines such as TNF-α, IL-6, IL-Iβ, IL-17, and IL-18." (PMID 37104352, 2023). "In this study, a cross-sectional analysis of multiple autoimmune disorders revealed that the expression of IFN-signature genes was high in autoimmune diseases such as SLE, and that IL-18 or IL-1β signature was high in autoinflammatory diseases such as Behcet’s disease." (PMID 35686127, 2022). "Although the role of IL-18 and sFas has been elucidated separately, in the pathogenesis of LN, there is little evidence about the correlation between sFas and IL-18 in autoimmune diseases." (PMID 23577265, 2013). "Additionally, for now there is development for treating autoimmune diseases in patients that are non-responsive or over time are refractory to treatment with TNF-α antagonists and/or T-cell co-stimulation antagonists with an IL-18 antagonist." (PMID 35457026, 2022).
type 2 diabetes (105 papers, 2010 to 2026). "Conversely, a decrease in IL-18 was associated with an improvement in β-cell function in individuals suffering from type 2 diabetes." (PMID 39962379, 2025). "The adipokine C-X3-C motif chemokine ligand 1 (CX3CL1, Fractalkine) and interleukin-18 (IL-18) both are associated with type 2 diabetes and are increased in the plasma of respective patients." (PMID 34281240, 2021). "In line with this randomized clinical trial, we conducted 2-sample mendelian randomization using DIAGRAM and show genetic evidence of an association of IL18 inhibition on type 2 diabetes (odds ratio, 0.89 [95% CI, 0.81-0.99]; eMethods in the Supplement)." (PMID 33263724, 2021). "Increasing levels of circulating IL-18 have been reported to be closely associated with the components of MetS and to predict type 2 diabetes, cardiovascular events, and mortality." (PMID 21251304, 2011). "In addition, the risk of developing type 2 diabetes was highest among subjects with elevated IL-18 and CRP or IL-18 and IL-6, respectively." (PMID 34829612, 2021). "Furthermore, IL-18 has been identified as the causal of multiple chronic diseases, such as type 2 diabetes." (PMID 32266232, 2020). "In the model adjusted for age, sex, survey and cardiometabolic risk factors (model 2), IL-18, adiponectin, sE-selectin and sICAM-1 were each significantly associated with incident type 2 diabetes with HRs betwen 1.11 and 1.67 (0.33 for the protective adipokine adiponectin)." (PMID 21674000, 2011). "Elevated levels of IL-18 have been associated with an increased risk of developing type 2-diabetes." (PMID 20809989, 2010). "IL-18 has been identified as a key immunometabolic mediator in the pathogenesis of both type 1 and type 2 diabetes." (PMID 40804870, 2025). "IL-18 was enriched in the “role of the inflammasome in macrophages, adipocytes, and pancreatic beta cells in type 2 diabetes” pathway by MetaCore." (PMID 36816031, 2023). "GSK1070806, a neo-IgG1 mAb that neutralizes IL-18, has been tested in a pilot trial in type 2 diabetes and kidney transplantation, and a corresponding RCT based on genomic detection of IL-18 in IBD is warranted." (PMID 36145301, 2022). "We performed univariate analysis of the relationships between the parameters of arterial stiffness and the IL-18 levels in patients with type 2 diabetes." (PMID 36263325, 2022). "Univariate analysis of relationship between logarithmic serum or urinary IL-18 levels and characteristics of type 2 diabetes." (PMID 36263325, 2022). "We showed that type 2 diabetes in this model is associated with renal inflammation, as indicated by the increased protein expression of inflammatory markers MCP1, TNFα, TGFβ, and IL-18." (PMID 32218769, 2020). "In the serum of the rats with HFD + STZ-induced type 2 diabetes, a decrease in the level of interleukin 18 (IL-18) and urea, as well as an increase in the ALT activity was observed when compared to the rats from the C group." (PMID 31771099, 2019). "Recently, an anti-IL18 monoclonal antibody, which decreased free IL18 levels, was found to be safe, yet ineffective in a phase II trial for type 2 diabetes." (PMID 31253830, 2019). "We analyzed caspase-1 activation and the IL-1β and IL-18 secretion in lipopolysaccharide (LPS)-primed bone marrow-derived macrophages (BMDMs) stimulated with ccf-DNA from patients with type 2 diabetes and poly(dA:dT), an AIM2 inflammasome activator." (PMID 30965677, 2019). "The IL-18 receptor is suggested to be the responsible molecular site for the observed IL-18 resistance, as leucocyte from obese and type 2 diabetics demonstrated a reduced IL-18 receptor expression on leucocyte." (PMID 29342149, 2018). "Obese subjects and person with type 2 diabetes demonstrate impaired IL-18 responsiveness in leucocyte despite increased circulating levels of IL-18." (PMID 29342149, 2018).
type 2 diabetes (continued). "Type 2 diabetes is associated with subclinical inflammation as indicated by the increase of circulating proinflammatory cytokines as such as TNF-α, IL-6, IL-1ß or IL-18." (PMID 29121068, 2017). "In age and sex adjusted model, EN-RAGE, IL13, IL17, complement 3, IL18, TNFRII, IL1ra and CRP were associated with incident type 2 diabetes." (PMID 28258520, 2017). "A recent pilot study in obese subjects with type 2 diabetes treated with IL-18 antibody for 12 weeks has shown a safe profile of the drug, tested at different doses, without impairing glucose metabolism." (PMID 28394363, 2017). "Tumor necrosis factor (TNF)-α, IL-18, IL-8, and C-reactive protein (CRP) are considered potential risk factors for the development of type-2 diabetes (T2D) and its associated metabolic complications." (PMID 27980459, 2016). "This suggests that IL-18 can be used as an index of the co-presence of type 2 diabetes and liver cancer whereas HGF is specific only for the cancer." (PMID 26226632, 2015). "The antidiabetic agents, dipeptidyl peptidase IV inhibitors, were found to reduce glucose fluctuations and plasma nitrotyrosine, IL-6, and IL-18 levels (p<0.05) in type 2 diabetic patients after 3 months of treatment." (PMID 25259806, 2014). "Others report that aerobic exercise training decreases plasma CRP, TNF-α and IL-18/IL-10 ratios in type 2 diabetics." (PMID 24324580, 2013). "Overall these data highlight that the simultaneous presence of CHC and type 2 diabetes induces an evident increase of the following proinflammatory cytokines: IL-1α, IL-2R, IL-12, IL-18, CXCL9, MIF and HGF." (PMID 22745767, 2012). "On the other hand, aerobic exercise has been reported to reduce levels of CRP and IL-18 in subjects with type 2 diabetes." (PMID 21251304, 2011). "IL-18 acts in synergy with IL-12 to stimulate Th1 polarisation, and levels of IL-12 have been reported to be increased in subjects with type 2 diabetes and by experimental hyperglycemia." (PMID 20331890, 2010). "Aerobic exercise has been reported to reduce levels of CRP and IL-18 in subjects with type 2 diabetes." (PMID 20331890, 2010). "Interestingly, a significant positive correlation existed between clinical periodontal parameters in type 2 diabetic patients, such as the gingival index, clinical attachment loss, periodontal inflamed surface area and salivary levels of AIM2, IFI16, and IL18." (PMID 41440367, 2025). "The levels of both IL-18 and IL-18BP were shown to be changed in type 2 diabetes in a recent study." (PMID 41465472, 2025). "Moreover, the increased production of IL-18 and IL-1β mediated by inflammasomes contributes to the onset and progression of RA, type II diabetes, and various neurodegenerative disorders, including Alzheimer’s disease (AD) and ALS51." (PMID 38036728, 2023). "In human monocytes, CASP5 and CASP4 could be activated by saturated fatty acids, then trigger IL‐1β and IL‐18 release, which contributed to type 2 diabetes." (PMID 32311223, 2020). "The circulating level of adiponectin inversely correlates with IL-18 in human with type 2 diabetes." (PMID 32545355, 2020). "By using 26,903 individuals with type 2 diabetes and 198 269 controls, we found that MR analyses did not support a role of IL18 in type 2 diabetes risk (OR = 1.05, 95% CI = 0.99–1.13, P-value = 0.12)." (PMID 31253830, 2019). "Consistently, the ccf-DNA (ccf-DNA #1 and ccf-DNA #2) from two independent patients with type 2 diabetes showed significantly higher IL-1β and IL-18 secretion in response to poly(dA:dT) as compared with the vehicle control, whereas the secretion of tumor necrosis factor (TNF)-α was unchanged." (PMID 30965677, 2019). "For example, enhancement of AMPK activity was shown to cause suppression of palmitate-induced inflammasomes activation, whereas deficiency of AMPK by a pharmacological inhibitor or siRNA enhanced IL-1β and IL-18 production in monocyte-derived macrophages from patients with type 2 diabetes." (PMID 28617316, 2017).
type 2 diabetes (continued). "Moreover, in two prospective cohorts, elevated levels of IL-18 have been shown to predict the development of type 2 diabetes." (PMID 20331890, 2010). "Although IL-18 has been ascribed a positive role in glucose homeostasis, a number of clinical studies have observed an upregulation of circulating IL-18 in patients with type 2 diabetes, independent of risk factors such as BMI and the presence of a generalized pro-inflammatory state." (PMID 39962379, 2025). "Moreover, IL-18 correlated also with glycemia as in type 2 diabetes patients." (PMID 22745767, 2012). "Furthermore, in a study of patients with type 2 diabetes, both carotid intima media thickness and brachial-ankle pulse wave velocity were significantly associated with serum levels of IL-18, although not in multivariate analyses." (PMID 20331890, 2010). "The mtDNA from patients with type 2 diabetes induced AIM2 inflammasome-dependent caspase-1 activation, and IL-1β and IL-18 secretion in macrophages." (PMID 30965677, 2019). "Certainly, these data are interesting since IL-18 is increased in both CHC and type 2 diabetes patients whereas C-peptide is increased only in CHC patients." (PMID 22745767, 2012). "The levels of MIF, insulin, ghrelin, leptin, glucagon, resistin and adipsin are similar in type 2 diabetes and CHD patients whereas IL-1α, IL-2R, IL-12, IL-18, HGF, and PAI-1 are higher in CHD patients than in type 2 diabetes patients (with p-value <0.01)." (PMID 22745767, 2012). "In conclusion, elevated IL-18, NFATC4, TNF-α, and IL-6 levels suggest inflammation is key in prediabetes pathogenesis, highlighting the need for further research into interventions to delay or prevent type 2 diabetes." (PMID 40027364, 2024). "In patients with type 2 diabetes, GLP-1RAs lowered the plasma levels of IL-18 and IL-1β." (PMID 41424495, 2024). "Interleukin-18 (IL-18) showed higher expression in the liver of pigs fed with the SOY diet and was enriched in the “role of the inflammasome pathway in macrophages, adipocytes, and pancreatic beta cells in type 2 diabetes”." (PMID 36816031, 2023). "Future studies are needed to compare the levels of these proteins between patients with type I vs. type II diabetes to differentiate whether type I and type II diabetes have different effects on the expression of ASC, IL-18, CRP, uPA, EGF, and NGAL." (PMID 35355862, 2022). "We initially examined salivary IL-18 levels in the controls and the type 2 diabetic patients and found that salivary IL-18 levels were not significantly different between the DM group and the control group." (PMID 32053656, 2020). "Patients with type 2 diabetes mellitus have higher plasma concentrations of pro-inflammatory cytokines, including IL-1β, IL-6, IL-8, IL-17, IL-18, TNF-α, IFN-γ, and TGF-β, according to research (T2DM)." (PMID 40149566, 2025). "Therefore the MR of IL18 on type 2 diabetes is consistent with trial results and suggests that further investigation of this therapy for type 2 diabetes may not be successful." (PMID 31253830, 2019). "Additionally, we observed an increase in plasma IL‐18 concentrations 6 h after meal consumption during normoxia, concurrent with previous findings showing an increase in serum IL‐18 concentrations 4 h after a high‐fat meal in individuals with and without type 2 diabetes." (PMID 37653582, 2023). "The mtDNA, from patients with type 2 diabetes, induced absent in melanoma 2 (AIM2) inflammasome-dependent caspase-1 activation and IL-1β and IL-18 secretion in macrophages." (PMID 30965677, 2019). "However, in another study, IL18, but not CRP or IL 6, was higher in patients with type 2 diabetes and cardiac autonomic neuropathy." (PMID 35329958, 2022). "Interestingly, in a population of type 2 diabetic patients with normal or high GFR, urine IL-18 was not different from healthy controls even if macroalbuminuria was present." (PMID 35204131, 2022).
type 2 diabetes (continued). "In PAD patients with type 2 diabetes, the IL-18 level is significantly higher than in non-diabetic PAD patients, which may suggest that IL-18 contributes to the extent of impaired perfusion recovery induced in diabetic patients with PAD." (PMID 29358309, 2018).
melanoma (101 papers, 2005 to 2026). A malignant, usually aggressive tumor composed of atypical, neoplastic melanocytes. "We demonstrate that the electrogenic transfer of ICD effector-encoding plasmids into mouse melanoma tumors when combined with intratumoral expression of cytokines IL-1β, IL-12, or IL-18, enhanced anti-tumor immune responses." (PMID 39737979, 2024). "In another study using 26 grey horses bearing melanomas, IL-12-encoding plasmid and IL-18-encoding plasmid were tested, leading to significant size reduction in tumors." (PMID 36670786, 2023). "In combination, the findings suggested that GZMA, GSDMB, NLRP1, CHMP4A, and IL18 deficiency, at least in part, are responsible for melanoma." (PMID 37620327, 2023). "The risk of toxicity for IL-18 TRUCKs is different to IL-12 TRUCKs that revealed severe toxicity of T cells engineered with inducible IL-12 in a melanoma mouse model due to off-target cytokine secretion." (PMID 35401506, 2022). "We have identified 4 inflammasome related Single Nucleotide Polymorphisms (SNPs) for CARD8 (rs6509365); IL1B (rs1143643) and IL18 (rs5744256 and rs1834481) related to melanoma susceptibility/protection." (PMID 27942564, 2017). "In a clinical study, twenty-seven, grey, melanoma-bearing, horses were assigned to three groups (n = 9) and vaccinated on days 1, 22, and 78 with DNA vectors encoding for equine (eq) IL-12 and IL-18 alone or in combination with either human glycoprotein (hgp) 100 or human tyrosinase (htyr)." (PMID 25967290, 2015). "Some clinical observations show that high serum levels of IL-18 in cancer patients may be associated with various NK cell defects, as well as that this cytokine may have the role in melanoma metastases." (PMID 25889680, 2015). "Confirming a mechanistic role for NK cells in the antitumor effects of sIL18, IL18-overexpressing B16-F10 melanomas progressed as rapidly as their IL18D69A-overexpressing counterparts in C57BL/6 mice subjected to the antibody-dependent depletion of NK cells." (PMID 40263267, 2025). "Subsequently, the NK cells were stimulated for 5 hours under different conditions (resting, IL-12 + IL-18, IL-15, B16-melanoma cells)." (PMID 39920136, 2025). "Administration of recombinant IL-18 synergized with the costimulatory ligand B7.1 to induce melanoma regression and early immunotherapies based on IL-18 have shown efficacy and the ability to generate antitumor responses." (PMID 38391959, 2024). "IL-18 has been shown to be detrimental in several types of cancer, including advanced gastric cancer, certain subsets of melanomas, and T-cell Acute Lymphoblastic Leukemia." (PMID 39769266, 2024). "Therapies that inhibit the NLRP3 inflammasome can block melanoma migration by suppressing the secretion of IL-1β and IL-18 cytokines and/or activating natural killer cells." (PMID 39275245, 2024). "By analyzing gene expression profiles of normal skin and melanoma cells, Li and colleagues reported a set of 5 key prognostic, differentially expressed PYR-associated genes (GSDM A, GSDM C, IL18, NLRP6 and AIM2)." (PMID 36674798, 2023). "This is supported by another study in melanoma and colon tumor mouse models showing that IL-18 induces the expression of PD-1 on NK cells." (PMID 37298187, 2023). "IL-18 can also promote liver metastasis of melanoma cells by regulating the expression of vascular cell adhesion molecule-1 and the adhesion of melanoma cells." (PMID 36707882, 2023). "We also reported decreased tumor sizes in lung metastasis models of melanoma treated with the combination of immune checkpoint inhibitors and IL18." (PMID 38139000, 2023). "In clinical trials, systematic administration of IL18 significantly suppressed the growth of several kinds of carcinomas, such as melanoma and renal cell cancer, by stimulating the immune system." (PMID 38139000, 2023). "It has been shown that IL-18 promotes the growth, angiogenesis, and metastasis of melanoma both in autocrine and paracrine manners." (PMID 37950289, 2023).